YBX1 (Y-box binding protein 1)
Diseases named in the same sentence as YBX1 in open-access papers (continued):
Sharing a sentence is not in itself a finding about the gene and the disease.
hepatocellular carcinoma (75 papers, 2009 to 2026). A malignant tumor that arises from hepatocytes. "The elevated expression of m1A methyltransferases (TRMT10C, TRMT6) and ribosomal RNA processing protein 8 (RRP8), along with m5C reader YBX1, demonstrate a significant association with unfavorable prognosis in hepatocellular carcinoma." (PMID 40699703, 2025). "In addition to the significant association of high YBX1 expression with survival in hepatocellular carcinoma patients, knockdown of YBX1 impaired cell proliferation by 50% resembling the effect of lincNMR knockdown." (PMID 32587247, 2020). "CircRNA-SORE, which is significantly associated with sorafenib resistance in hepatocellular carcinoma, could bind with the oncogenic protein YBX1 in the cytoplasm and inhibit its interaction with the E3 ubiquitin ligase PRP19, thereby suppressing ubiquitin–proteasome-mediated degradation of YBX1." (PMID 36038948, 2022). "With regard to liver disorders, the roles of YBX1 have been extensively explored in liver fibrosis and hepatocellular carcinoma." (PMID 40083711, 2025). "USP2-AS1 enhances YBX1-HIF1α mRNA binding under hypoxia, increasing HIF1α protein levels and hepatocellular carcinoma growth." (PMID 40799245, 2025). "A prior investigation validated that YBX1 has the ability to trigger the expression of PD-L1 by attaching to a motif in the PD-L1 promoter, thereby amplifying drug resistance in hepatocellular carcinoma." (PMID 38698857, 2024). "This interaction unveils a potential therapeutic avenue by combining IRGM inhibition with immune checkpoint inhibitors, highlighting YBX1’s pivotal role in the regulation of immune responses in hepatocellular carcinoma." (PMID 38255791, 2024). "Specifically, YBX1-mediated upregulation of PD-L1 has been shown to facilitate immune evasion and chemoresistance in hepatocellular carcinoma (HCC)." (PMID 38520004, 2024). "In hepatocellular carcinoma, YBX1 inhibits the maturation of miR-205 and miR-200b, leading to increased expression of ZEB1 and subsequently enhancing cell migration and invasion." (PMID 38255791, 2024). "For example, circRNA-SORE binds to YBX1 protein and subsequently blocks PRP19-mediated YBX1 degradation to promote sorafenib resistance in hepatocellular carcinoma." (PMID 38378679, 2024). "In the setting of stress-promoted carcinogenesis, the Y box binding protein-1 (YB-1) was previously reported to link adrenergic signaling to β-catenin mediated chemoresistance in hepatocellular carcinoma and pancreatic cancer." (PMID 38962320, 2024). "There is growing evidence that YBX1 can interact with multiple lncRNAs and regulate tumor progression in a variety of cancers, including hepatocellular carcinoma 49-51." (PMID 35541917, 2022). "Further, the results of transwell assays found that co-transfection of Linc01612 and YBX1 can partly recover the invasion ability of hepatoma cells as compared with co-transfection of Linc01612 and vector." (PMID 35541917, 2022). "The results of clone formation assays showed that co-transfection of Linc01612 and YBX1 partly recovered the proliferation ability of hepatoma cells when compared with co-transfection of Linc01612 and vector." (PMID 35541917, 2022). "For example, circRNA-SORE mediates sorafenib resistance in hepatocellular carcinoma by targeting YBX1." (PMID 35575762, 2022). "For instance, circRNA-SORE increases sorafenib resistance by stabilizing YBX1 in hepatocellular carcinoma." (PMID 35831872, 2022). "HBx-downregulated lncRNA GAS5 inhibits the cell viability and invasion of hepatocellular carcinoma cell lines by activating Y-box-binding protein 1/p21 (YBX1/p21) signaling." (PMID 34830378, 2021). "YBX1 promotes the progression of hepatocellular carcinoma by inhibiting ferroptosis." (PMID 41180455, 2025). "YBX1 was reported to be O-GlcNAcylated in hepatocellular carcinoma." (PMID 38575607, 2024).
hepatocellular carcinoma (continued). "A recent report showed that YBX1 supports immune evasion in hepatocellular carcinoma cells by decreasing the release of important inflammatory cytokines such as IL10 and TGFβ, further underlining our findings of a negative regulation of apoptosis-related cytokines and chemokines in medulloblastoma." (PMID 32585856, 2020). "Conversely, Immune-related GTPase (IRGM) binds directly to YBX1, facilitating its phosphorylation and nuclear localization, which subsequently upregulates Programmed Death-Ligand 1 (PD-L1) expression and promotes the malignant progression of hepatocellular carcinoma." (PMID 39727969, 2024). "Y-box binding protein 1 (YB-1) overexpression has been shown in various tumor cells including hepatocellular carcinoma (HCC); moreover, this protein can be actively secreted." (PMID 24069038, 2013). "lncRNA-AWPPH interacts with YBX1, promoting SNAIL1 translational activation and hepatocellular carcinoma progression." (PMID 40799245, 2025). "Additionally, YBX1 knockout can reverse hepatocellular carcinoma (HCC) resistance by blocking PD-L1 expression and activating T cells in the tumor microenvironment." (PMID 40370440, 2025). "In hepatocellular carcinoma, IRGM enhances the interaction between YBX1 and S6K1 kinase, increasing YBX1 phosphorylation and nuclear localization, and enhancing PD-L1 transcription." (PMID 40799245, 2025). "Intrahepatic cholangiocarcinoma (ICC), the second most common primary liver cancer after hepatocellular carcinoma (HCC), exhibits high YBX1 expression, which correlates with poor patient prognosis." (PMID 41346602, 2025). "The reader protein YBX1 recognizes m5C-modified mRNA and recruits ELAVL1 to stabilize hepatoma-derived growth factor mRNA, thus facilitating bladder cancer cell growth and metastasis." (PMID 39164641, 2024). "The LLPS of YBX1 enhanced by circASH2 promotes the decay of TPM4 transcripts, effectively inhibiting the metastasis of hepatocellular carcinoma by mediating cytoskeleton remodeling." (PMID 39749343, 2024). "Linc01612 promotes the ubiquitination and proteasome pathway degradation of YBX1, thereby reducing YB1 protein stability, reducing YB1 protein levels, but not affecting its RNA expression levels, exerting its inhibitory effect in hepatocellular carcinoma." (PMID 39497723, 2024). "In hepatocellular carcinoma, circRNA-SORE binds the major oncogenic protein YBX1 in the cytoplasm thereby preventing the nuclear interaction of YBX1 with the E3 ubiquitin ligase PRP19 thereby reducing YBX1 levels." (PMID 37340423, 2023). "In hepatocellular carcinoma, GAS5 attenuates cell viability and invasion by boosting p21 expression via binding YBX1." (PMID 37639158, 2023). "In the nucleus of hepatocellular carcinoma (HCC) cells, the interaction between MIR4435-2HG and the DNA binding protein Y-box binding protein 1 (YBX1) can enhance the binding of YBX1 to the PI3K promoter, thereby promoting the transcription of PI3K." (PMID 35784328, 2022).
hepatocellular carcinoma (continued). "Also, the expression of YBX1 mRNA significantly positively correlated with RRM2, TK1, and TYMS mRNA expression in 374 human hepatocellular carcinoma samples (TCGA)." (PMID 32587247, 2020). "In addition, genetic interventions targeting PPM1B/USP10-Y-box binding protein 1 (YBX1) axis or lysophosphatidylcholine acyltransferase 1 (LPCAT1) enhance PANoptosis-related protein activation, effectively suppressing gastric and hepatocellular carcinoma progression." (PMID 40721869, 2025). "CircASH2 enhances the LLPS of nuclear Y-box binding protein 1 (YBX1) in hepatocellular carcinoma, and also enhances the attenuation of the primary target protein tropomyosin 4 (TPM4) transcripts, thereby altering the tumor cytoskeleton structure to inhibit HCC metastasis." (PMID 38546385, 2024).
lung cancer (61 papers, 2008 to 2026). A malignant neoplasm involving the lung. "In recent, several in vivo loss-of-function studies showed that silencing of YBX1 suppressed tumorigenesis, such as liver cancer and lung cancer." (PMID 29029484, 2017). "Considering the vital function of YBX1 and hY4F in the progression of lung cancer confirmed in cell and animal levels, we wondered whether they are associated with clinical oncogenesis or prognosis of lung cancer patients." (PMID 35410432, 2022). "The survival analysis and immune cell infiltration analysis revealed that YBX1 promotes the progression of lung cancer." (PMID 40176113, 2025). "A previous study showed that YBX1 is highly expressed in numerous cancers, such as lung cancer, and the Hippo pathway has a role in lung carcinogenesis." (PMID 39313797, 2024). "The clinical importance of YBX1 expression in cancer ought to be evaluated in a sex-specific manner, especially in lung cancer." (PMID 38538658, 2024). "At this threshold, sex differences in YBX1 expression for the Lung cancer cohort were highly significant with a Cohen’s D of 0.363, indicating a medium to large effect size." (PMID 38538658, 2024). "In lung cancer, it has been documented that YBX1 mediates the upregulation of TGFBR1, consequently enhancing TGFβ1 signaling." (PMID 38255791, 2024). "Future studies aimed as assessing he biological functions and clinical importance of YBX1, and its protein product in cancer ought to consider the biological sex of their models and patients, especially in lung cancer." (PMID 38538658, 2024). "A violin plot of the YBX1 expression distribution indicates higher expression in males, compared to females in lung cancer." (PMID 38538658, 2024). "It is reported that YBX1 directly binds to lncRNALINC00312 to promote lung cancer cell invasion, migration, and angiogenesis." (PMID 37170222, 2023). "Mechanically, circRABL2B retards lung cancer progression by synergizing YBX1 to degrade MUC5AC mRNA and impoverish cancer cell stemness." (PMID 37324942, 2023). "Another study reported that long noncoding RNA Linc00857 interacting with YBX1 to regulate autophagy and proliferation of lung cancer cells through MET proto-oncogene (MET)/AMPK signaling." (PMID 36642732, 2023). "Flow cytometry results showed that the percentage of apoptotic cells was significantly increased in YBX1 downregulated lung cancer cells, while decreased in YBX1 overexpressed cancer cells." (PMID 35410432, 2022). "And flow cytometry analysis demonstrated that the apoptotic ratio was significantly increased in YBX1 knockout lung cancer cells." (PMID 35410432, 2022). "Analysis of cell viability using CCK-8 assay and EdU assay showed that knockdown of YBX1 inhibited lung cancer cell proliferation, while overexpression of YBX1 promoted proliferation." (PMID 35410432, 2022). "Our findings demonstrate that hY4F acts as a tumor suppressor and is selectively sorted into lung cancer cell-derived EVs by interacting with methylated YBX1, which in turn promotes lung cancer progression." (PMID 35410432, 2022). "In this study, we reveal that hY4F are upregulated in NSCLC-derived EVs, and that the selective sorting and secretion of hY4F into lung cancer EVs is regulated by the RNA-binding protein Y box binding protein 1 (YBX1)." (PMID 35410432, 2022). "In this paper, we confirmed that hY4F is selectively sorted into EVs by binding with YBX1 to serve as a tumor suppressor which downregulating MAPK/NF-κB signaling pathway in lung cancer." (PMID 35410432, 2022).
lung cancer (continued). "Taken together, these data suggest that SETD3 is involved in regulating the methyl-YBX1/EVs-hY4F pathway and plays an important role in the progression of lung cancer cells." (PMID 35410432, 2022). "Collectively, these results indicate that YBX1 binds hY4F to regulate its sorting and secretion into EVs in lung cancer." (PMID 35410432, 2022). "Post-translational modification of several RBPs like YBX1 help in sorting ncRNA inro exosomes, like methylation of YBX1 aids to sort hY4F which functions as a tumor suppressor which in turn promotes lung cancer growth." (PMID 36362424, 2022). "Consistent with this, the level of YBX1 protein in lung cancer patients correlated positively with tumor stage and grade." (PMID 35410432, 2022). "Transcriptome sequencing, qRT-PCR validation, bioinformatics analysis and NF-κB pathway inhibitor assays elucidate the mechanism of YBX1 and hY4F inhibiting lung cancer." (PMID 35410432, 2022). "LINC01133 exerts oncogenic functions in nasopharyngeal carcinoma and lung cancer by binding to YBX1 and EZH2, respectively." (PMID 34047479, 2021). "All these results show that YBX1 is involved in the control of migration and invasion of lung cancer cells." (PMID 34976785, 2021). "Our composite research includes bioinformatics analysis, retrospective cohort study, mechanisms in vitro, and different animal models, which make an important complement to the study of YBX1 affecting growth and metastasis mechanisms in lung cancer." (PMID 34976785, 2021). "YBX1 has been considered a therapeutic target for a long time, even the antisense DNA complex of YBX1 has been developed to silence YBX1 in lung cancer cells." (PMID 34976785, 2021). "MIR22HG was also down-regulated in lung cancer and interacts with YBX1, MET and p21 to suppress cancer development." (PMID 32500915, 2020). "Consistent with this, we have previously confirmed that both MET protein and mRNA were decreased after YBX1 knockdown in lung cancer cells." (PMID 33312753, 2020). "The oncogenic role of YBX1 in different kinds of tumors, including breast and lung cancer, have been also reported in recent years 55-57." (PMID 32929382, 2020). "CAR10 is upregulated by carcinogen dibenz[a,h]anthracene that increases proliferation of lung cancer cells by binding transcription factor Y-box-binding protein 1 (YB-1)." (PMID 30617305, 2019). "In this study, we found that LINC00312 induced migration, invasion and VM of lung cancer cells by direct binding to the transcription factor Y-Box Binding Protein 1 (YBX1)." (PMID 30470227, 2018). "Collectively, these results demonstrate inhibition of YBX1 suppressed lung cancer growth partly via the CDC25a pathway and high expression of YBX1/CDC25a predicts poor prognosis in human lung adenocarcinoma." (PMID 27384875, 2016). "Our study reveals that YBX1 activates CDC25a expression and suggests that the YBX1/CDC25a axis is involved in the cancer development and progression of human lung cancers." (PMID 27384875, 2016). "In this study, we analyzed the expression and clinical significance of YBX1 and CDC25a in lung adenocarcinoma and identified their roles in the regulation of lung cancer growth." (PMID 27384875, 2016). "Subsequently, we found that knockdown of YBX1 by siRNA significantly decreased CDC25a activity and inhibited growth in vitro and in vivo, which indicated the key role of YBX1/CDC25a axis involved in lung cancer development and progression." (PMID 27384875, 2016). "LINC00857 is upregulated in lung cancer cells by a mechanism that involves LINC00857 binding to YBX1, preventing its proteasomal degradation, increasing its nuclear translocation, and promoting MET expression to regulate biological processes such as cell proliferation." (PMID 41507135, 2026). "LINC00312 directly binds to YBX1, inducing lung cancer cell migration, invasion, and angiogenesis." (PMID 40799245, 2025).